FTH1 (ferritin heavy chain 1)
Diseases named in the same sentence as FTH1 in open-access papers (continued):
Sharing a sentence is not in itself a finding about the gene and the disease.
Alzheimer disease (7 papers, 2021 to 2025). A progressive, neurodegenerative disease characterized by loss of function and death of nerve cells in several areas of the brain leading to loss of cognitive function such as memory and language. "With aging, the Fth1/Ftl1 ratio increases, accompanied by a shift of Fth1 to fine processes, whereas in Alzheimer’s disease, this ratio decreases, redistributing Fth1 to the soma and Ftl1 to large processes near amyloid beta (Aβ) deposits." (PMID 41150779, 2025). "In addition, there was a significant decrease in transcripts for ferritin light chain (FTL) and ferritin heavy chain (FTH1) in the cerebellum of patients with Alzheimer’s disease, which also had a significant reduction in ferroportin." (PMID 38667304, 2024). "Prior research confirmed that the occurrence of ferroptosis in the Alzheimer’s disease mouse model was accompanied by a significant decrease in SLC7A11, SLC3A2, and FTH1 and an increase in the protein expression of DMT1 and NCOA4." (PMID 39635435, 2024).
colon cancer (7 papers, 2021 to 2025). "For example, M2 macrophages have been shown to promote colon cancer cell proliferation by delivering ferritin heavy chain (FTH1) protein via exosomes." (PMID 40873588, 2025). "Immunoblotting analysis showed that TFRC and FTH1 protein expression were reduced in colon tumors from CDX2ERT2TfrcF/FApcF/+ mice." (PMID 36703617, 2023). "In silico analysis further supported these observations; in that, the expression of IRP-1, HMOX-1, and FTH1 expression was significantly decreased while that of HAMP (Hepcidin) was significantly increased in primary colon tumor tissue compared to normal tissue." (PMID 39097854, 2024). "Therefore, the increased expression levels of FTH1 in AOM/DSS mice could have contributed to the development of colon cancer." (PMID 35631174, 2022). "Analysis of human colon tumor tissue revealed decreased expression of IRP-1, HMOX-1, and FTH1 but increased HAMP expression." (PMID 39097854, 2024). "Low FTH1 levels in either high- or low-iron diet-fed mice could have led to an increase in LIP levels, oxidative stress, and cell death, resulting in the alleviation of colon cancer development in both ID and IOL mice." (PMID 35631174, 2022). "Overall, this study suggests that AOM/DSS-induced colon cancer did not induce iron accumulation in the liver and colon of AOM/DSS-treated mice, but rather reduced tissue iron levels, especially LIPs in colon tissue, which might have decreased because of the increase in colonic FTH1." (PMID 35631174, 2022).
head and neck squamous cell carcinoma (7 papers, 2021 to 2024). A squamous cell carcinoma that arises from any of the following anatomic sites: lip and oral cavity, nasal cavity, paranasal sinuses, pharynx, larynx, and salivary glands. "For instance, in the head and neck squamous cell carcinoma, FTH1 suppressed ferroptosis and led to the poor prognosis of the carcinoma." (PMID 35345408, 2022). "We previously showed that expression of ferritin light chain (FTL) and ferritin heavy chain (FTH1) subunits is increased in head and neck squamous cell carcinoma (HNSC)." (PMID 33864445, 2021). "To substantiate the prognostic significance of our model, we recruited a clinical cohort consisting of 20 patients with head and neck squamous cell carcinoma at various clinical stages to verify the expression of the four genes (CCND1, FTH1, YWHAG and TNFRSF12A)." (PMID 37882107, 2024). "We previously showed that FTH1 and FTL have positive linear correlation and the protein expression levels of both were higher in head and neck squamous cell carcinoma (HNSC) tumor tissues compared with normal tissues, and that elevated FTH1 was related to poorer prognosis." (PMID 33864445, 2021). "Currently, ferritin heavy chain (FTH1) has been increasingly found to play a crucial role in cancer as a core regulator of ferroptosis, while its role of non-ferroptosis in head and neck squamous cell carcinoma (HNSCC) is still unclear." (PMID 38025726, 2023).
iron overload (7 papers, 2017 to 2025). "High levels of serum ferritin (encoded by FTH1), a biomarker of body iron overload, were significantly associated with a high prevalence of hand osteoarthritis among participants (n = 1 241) of Xiangya Osteoarthritis Study (P-for-trend = 0.037)." (PMID 37914703, 2023). "The knockdown of ferritin heavy chain 1 (FTH1) facilitates iron overload–associated cardiomyopathy through ferroptosis." (PMID 37190037, 2023). "The upregulation of Fth1 and the downregulation of Tfrc suggest a reduction in the ability of the cell to uptake iron, which is also a protective measure against iron overload." (PMID 38057699, 2023). "In this regard, ferritin heavy chain 1 (FTH1) is a key subunit of the ferritin that stores iron in its non-toxic ferric form, and it plays a critical role in the maintenance of iron homeostasis in cells to prevent harmful effects caused by iron overload." (PMID 30071685, 2018).
triple-negative breast carcinoma (7 papers, 2017 to 2024). An invasive breast carcinoma which is negative for expression of estrogen receptor (ER), progesterone receptor (PR), and human epidermal growth factor receptor 2 (HER2). "Liu showed that a high cytoplasmic FTH1 level correlates with a favorable prognosis, whereas nuclear FTH1 is an adverse indicator, in triple negative breast cancer patients." (PMID 33864445, 2021). "They showed that piR-FTH1 downregulates Fth1 mRNA in triple-negative breast cancer (TNBC) cells, namely, MDA-MB-231, which indicates a potential therapeutic strategy for reducing FTH1 levels in cancer cells." (PMID 39717847, 2024).
anemia (6 papers, 2023 to 2026). A reduction in the number of red blood cells, the amount of hemoglobin, and/or the volume of packed red blood cells. "Specifically, FTH1 participates in ferritinophagy and ferroptosis and is linked to anaemia in GlycoA+ nucleated erythrocytes of MDS patients." (PMID 39804099, 2025). "Higher FTH1 was strongly associated with a reduced prevalence of anemia, defined by sex-specific criteria, in unadjusted analyses at entry (FTH1: β = −0.84, 95% CI: −1.1 to −0.58, p < 0.001 for all PWH)." (PMID 39334701, 2024). "By contrast, higher FTH1 levels in all PWH in our study were strongly associated with reduced anemia, another key contributor to NCI in this population." (PMID 39334701, 2024). "We investigated the association between FTH1 levels and anaemia in MDS." (PMID 39804099, 2025). "This study offers new insights into the treatment of MDS‐related anaemia by highlighting the potential therapeutic value of targeting FTH1." (PMID 39804099, 2025). "FTH1 was implicated in both ferritinophagy and ferroptosis in MDS patients, processes that are linked to the development of anaemia." (PMID 39804099, 2025). "This suggested that FTH1 exerts an influence on both cell proliferation and cell death, which is intricately tied to the manifestation of anaemia." (PMID 39804099, 2025). "In keeping with their iron-delivery and anti-ferroptosis roles, we also explored associations of FTH1 and FTL with anemia and isoprostanes (specific markers of in vivo oxidative stress) in PWH." (PMID 39334701, 2024). "In conclusion, the process of ferritinophagy involving FTH1 presents a novel concept for the primary mechanism underlying ineffective haematopoiesis in MDS and suggests that FTH1 may emerge as a promising therapeutic target for MDS‐related anaemia." (PMID 39804099, 2025). "Consequently, we sought to investigate whether alterations in FTH1 levels impact the degree of ferroptosis contributing to MDS‐related anaemia." (PMID 39804099, 2025). "Reduced expression of iron-handling genes (Hamp, Hamp2, Ftl1, Fth1) highlights the likelihood of diet-dependent regulation of hepatic iron metabolism, a notable concern post-RYGB where conditions of anemia often arise." (PMID 41598416, 2026).
cardiomyopathy (6 papers, 2021 to 2025). A disease of the heart muscle or myocardium proper. "In a genetic mouse model with heart‐specific conditional knockout of FTH1, overexpression of Slc7a11 effectively reverses cardiomyopathy caused by FTH1 deficiency by blocking ferroptosis in cardiomyocytes." (PMID 39568773, 2024). "Previously, no study has directly linked FTH1 to SIC; but based on our result, there may be a connection between FTH1 and the onset and progression of cardiomyopathy." (PMID 38025678, 2023).
viral infection (6 papers, 2016 to 2025). "Expression of FTH1 could be used to predict availability of cell model for DHBV/HBV infection or to screen anti-virus infection chemicals." (PMID 26900848, 2016). "Furthermore, the expression of FTH1 gradually increases with viral infection." (PMID 40661982, 2025). "This suggests that viral infection may upregulate ACSL4, activating ferroptosis, but it also upregulates the expression of SLC7A11 and FTH1 to inhibit the ferroptosis process." (PMID 40661982, 2025). "To analyze the role of the interacting proteins during viral infection, we examined previously published proteomic databases and found that EEF2, ANXA1, ANXA5, SLADRA, CLTA, and FTH1 were significantly enriched and FTH1 was notably upregulated in ASFV-infected PAMs." (PMID 40661982, 2025). "Additionally, the study observed that viral infection increases the expression levels of ACSL4, FTH1, and SLC7A11, but they gradually decrease as the viral infection progresses." (PMID 40661982, 2025). "Notably, the protein levels of FTL in the SUIT-2/shFTH1#3 cells were significantly altered after shFTH1 viral infection compared with those in either the SUIT-2 or the Scr cells; therefore, we specifically selected the sh#1 and sh#4 FTH1-knockdown clones for further analyses." (PMID 39294443, 2024).
asthma (5 papers, 2022 to 2025). "Asthma has been shown to reduce the expression of heavy‐chain ferritin (FTH1), which increases inflammation and oxidative stress." (PMID 38018577, 2023). "On the other hand, since TGF‐β expression has been shown to suppress the MAPK/ERK/c‐jun pathway, targeting TGF‐β in asthma patients can increase FTH1 expression and reduce inflammation and oxidative stress." (PMID 38018577, 2023). "In addition, we found that the expression of FTL and FTH1 was suppressed in the lung tissues of asthma model mice." (PMID 35154576, 2022). "Our study revealed that the model group presented elevated levels of NCOA4 and Beclin1 in lung tissue, whereas FTH1 and P62 expression were downregulated, suggesting that NCOA4‐mediated ferroautophagy is activated during asthma." (PMID 40667723, 2025). "SC remarkably facilitated the protein expression of FTH1 (P<0.05) and GPX4 (P<0.01), and suppressed the MDA and Fe2+ levels in the asthma cell model (P<0.05) compared with the model group." (PMID 37970439, 2023). "In our study, we observed a decreased expression of FTH1 and GPX4 in asthma mice, indicating ferroptosis occurred in asthma." (PMID 37970439, 2023). "The mRNA and protein expressions of FTH1 and GPX4 were significantly increased in the lung tissues of the SC group compared with the asthma group (P<0.05)." (PMID 37970439, 2023). "Accordingly, FTL and FTH1, two main ferritins responsible for iron storage, were upregulated in BALF of asthma mice." (PMID 35154576, 2022).
atherosclerosis (5 papers, 2022 to 2025). A disease characterized by the build-up of fatty material and calcium deposition in the arterial wall resulting in partial or complete occlusion of the arterial lumen. "Growing evidence suggests that the activation of ferritinophagy leads to the degradation of FTH1 in various pathological conditions, including neuroinflammation, lung injury, and atherosclerosis." (PMID 40278601, 2025).
cardiac hypertrophy (5 papers, 2018 to 2024). "Increase in expression of iron regulatory proteins TF, Tfrc, Fth-1, and Ftl-1 were also observed in heart tissues of rats which underwent constriction of the aorta and had cardiac hypertrophy." (PMID 31511561, 2019). "Fisetin improved the myocardial function by alleviating cardiac dysfunction, ameliorating myocardial fibrosis, mitigating cardiac hypertrophy in DOX-induced rats, and increasing the expressions of SIRT1/Nrf2 pathway genes, HO-1 and FTH1, in rats and H9c2 cells." (PMID 35273493, 2021).
cervical cancer (5 papers, 2021 to 2026). A primary or metastatic malignant neoplasm involving the cervix. "Co-treatment with 3-MA or overexpression of Cdc25A upregulated p62 and FTH1 levels and downregulated the LC3-II/LC-I ratio and TfR1 level in sorafenib-treated cells, indicating that overexpression of Cdc25A suppressed sorafenib-induced autophagy in cervical cancer cells." (PMID 34743185, 2021).
colorectal cancer (5 papers, 2021 to 2024). A primary or metastatic malignant neoplasm that affects the colon or rectum. "Previous studies have linked down-regulated ferritin heavy chain 1 (FTH1) expression to cancer progression in breast- and colorectal cancer, suggesting a role for the ferritin subunit in tumor suppression." (PMID 35447901, 2022). "So far, we have demonstrated that GPX4 and FTH1 are upregulated in anti-colorectal cancer drug-tolerant persister cells and tumors." (PMID 35719967, 2022). "Next, we detected the GPX4 and FTH1 levels in colorectal cancer patients undergoing neoadjuvant chemoradiotherapy by immunohistochemistry, and found both protein levels were up-regulated, compared with the patients without neoadjuvant chemoradiotherapy." (PMID 35719967, 2022). "Nevertheless, apart from two studies showing that FTL is elevated in GBM and colorectal cancer, little is known about the expressions of FTL and FTH1 in cancer." (PMID 33864445, 2021).
hypertrophic cardiomyopathy (5 papers, 2021 to 2025). A condition in which the myocardium is hypertrophied without an obvious cause. "Additionally, genetic ablation of ferritin heavy chain (FTH1) specifically in heart or neurons aggregates ferroptosis associated hypertrophic cardiomyopathy or traumatic brain injury, respectively." (PMID 34732689, 2021). "FTH has ferroxidase activity and mice lacking FTH1 in cardiomyocytes, when exposed to a high-iron diet, experience increased lipid peroxidation and hypertrophic cardiomyopathy." (PMID 41007630, 2025).
ischemia (5 papers, 2011 to 2025). A hypoperfusion of the BLOOD through an organ or tissue caused by a PATHOLOGIC CONSTRICTION or obstruction of its BLOOD VESSELS, or an absence of BLOOD CIRCULATION. "During ischemia and the initial stages of reperfusion, FTH1 breakdown releases iron, driving the iron‐dependent Fenton reaction, which results in oxidative damage and a subsequent decline in cardiac function associated with I/R injury." (PMID 39568773, 2024).
myocardial infarction (5 papers, 2020 to 2025). Gross necrosis of the myocardium, as a result of interruption of the blood supply to the area, as in coronary thrombosis. "We further examined the function of FTH1, and the results showed that overexpression of FTH1 reduced the size of myocardial infarction." (PMID 37370086, 2023).
pulmonary fibrosis (5 papers, 2023 to 2024). Chronic progressive interstitial lung disorder characterized by the replacement of the lung tissue by connective tissue, leading to progressive dyspnea, respiratory failure, or right heart failure. "In research about pulmonary fibrosis, FTH1 is involved in ferroptosis, whereas P62 and STAT1 are involved in autophagy." (PMID 38147026, 2023). "Bleomycin-induced lung fibrosis and FA-induced kidney fibrosis resulted in substantially elevated messenger RNA levels of the iron-storage protein ferritin (Fth1 and Ftl)." (PMID 38097808, 2023). "Nrf2 induces the expression of antioxidant genes including glutathione S-transferase (GST), NAD(P)H: quinone oxidoreductase 1 (NQO1), Hemeoxygenase1 (HO1), and ferritin heavy chain 1 (FTH1), which have been shown to protect against pulmonary fibrosis in murine models." (PMID 37875506, 2023).
Stroke (5 papers, 2019 to 2025). Sudden impairment of blood flow to a part of the brain due to occlusion or rupture of an artery to the brain. "Melatonin improves stroke by inhibiting autophagy-dependent ferroptosis mediated by NCOA4 binding to FTH1." (PMID 39959423, 2025). "The pooled results show that, compared to the model group, acupuncture significantly reduces iron ion deposition (lowering iron content) and promotes iron metabolism (reducing FTH1 and TfR1 levels) in brain tissue after stroke, thereby inhibiting ferroptosis." (PMID 40842100, 2025). "Our meta‐analysis indicates that acupuncture reduces post‐stroke iron accumulation in brain tissue, downregulates TFR1 and FTH1 levels, inhibits iron overload, and modulates iron metabolism." (PMID 40842100, 2025).
thyroid cancer (5 papers, 2012 to 2025). "Our results confirmed that a combination of IDET and taxol reduces the mRNA expression of NQO1, HO‐1, GCLM, and FTH1 in thyroid cancer cells." (PMID 41394539, 2025). "In advanced thyroid cancer, the balance between iron accumulation, lipid peroxidation, and antioxidant systems such as GPX4 and FTH1 is critical for regulating ferroptosis." (PMID 39917169, 2025).
astrocytoma (4 papers, 2017 to 2024). "We previously demonstrated that FTH1 knockdown enhanced therapeutic sensitivity in an astrocytoma cell line." (PMID 31491006, 2019). "Indeed, unlike astrocytoma cells, we have shown that GICs have increased sensitivity to FTH1 knockdown even in the absence of radiation implying that oxidative damage resulting from decreased FTH1 is sufficient to overwhelm the robust antioxidant systems possessed by these cells." (PMID 31491006, 2019). "Unlike astrocytoma cells that showed impairment of ATM phosphorylation and therefore were presumably unable to activate ΥH2AX, we found increased levels of phospho-ΥH2AX in GICs after FTH1 knockdown." (PMID 31491006, 2019).
head and neck cancer (4 papers, 2020 to 2025). A primary or metastatic malignant neoplasm affecting the head and neck. "Both FTL and FTH1 stained strongly in head and neck cancer tissues compared to normal and higher expression was observed with metastasis, however further analyses of public data found FTL had no prognostic significance but high FTH1 mRNA predicted poor survival." (PMID 32328462, 2020).
nasopharyngeal carcinoma (4 papers, 2015 to 2023). A carcinoma arising from the nasopharyngeal epithelium. "Surprisingly, the expression of ferritin heavy chain 1 (FTH1) was significantly higher in all nasopharyngeal carcinoma cells (CNE-2, S18, and S26) compared with tongue squamous cell carcinoma, as well as laryngeal squamous cell carcinoma cells." (PMID 36012290, 2022). "We discovered that nasopharyngeal carcinoma cells, which express a low level of KRAS and a high level of FTH1, are resistant to Erastin and RSL3." (PMID 36012290, 2022). "For example, the growth of HeLa and nasopharyngeal carcinoma (NPC) cells, was significantly reduced due to FTH1 overexpression." (PMID 27732930, 2016). "Additionally, nasopharyngeal carcinoma cells (CNE-2), which express a high level of FTH1 and a low level of EGFR, are insensitive to ferroptosis induction and EGFR inhibition." (PMID 36012290, 2022).